IL1B (interleukin 1 beta)
Diseases named in the same sentence as IL1B in open-access papers (continued):
Sharing a sentence is not in itself a finding about the gene and the disease.
mastitis (continued). "Previous studies have shown that through the activation of the NF-κB signaling pathway, miR-142 induces the release of cytokines such as TNF-α, IL-1β, IL-6, and IL-8, suggesting its pro-inflammatory role in the mastitis process." (PMID 40001538, 2025). "This was accompanied by breast tissue damage and a significant elevation in the levels of the proinflammatory cytokines TNF-α and IL-1β, suggesting the occurrence of mastitis." (PMID 40641870, 2025). "The results demonstrated that CB significantly alleviated LPS-induced mastitis by downregulating the expression of pro-inflammatory factors IL-1β, TNF-α, and the NLRP3 inflammasome while also reducing cell apoptosis." (PMID 40243637, 2025). "Accordingly, a high relative transcript level of TNF-α has been observed in SCs from buffalo with subclinical mastitis followed by IL-1B, IL-6, and IFN-γ." (PMID 39858163, 2025). "Previous studies have also reported greater concentrations of IL-1β and TNFα in milk from mastitis-affected women." (PMID 39896819, 2024). "A recent study found that daidzein significantly alleviated LPS-induced mastitis in mouse mammary gland epithelial cells by inhibiting IL-6 and IL-1β levels and suppressing the activation of MAPK/NF-κB signaling pathways." (PMID 39199398, 2024). "Proinflammatory cytokines are involved in the pathological process of mastitis, mainly including TNF-α, IL-1β, and IL-6, which are associated with the NF-κB pathway that regulates the production of cytokines and is involved in mastitis pathogenesis." (PMID 37948460, 2023). "Several studies have showed that the modulation of ERK and MAPK signaling pathway can lead to anti-inflammatory role in mastitis due to the decreased release of pro-inflammatory cytokines such as tumor necrosis factor-α, IL-1β, and IL-6." (PMID 37016420, 2023). "Data about subclinical and clinical mastitis demonstrate inflammatory responses to the intramammary infection driven by IL-1β, IL-6, and TNF-α." (PMID 36899749, 2023). "Proinflammatory cytokines including TNF‐α and IL‐1β are closely related to the development and progression of mastitis." (PMID 37644785, 2023). "TAC, Fb, ferritin, IL-1α, and IL-1β are valuable indicators for camel mastitis, but larger-scale studies on these markers are recommended." (PMID 37534071, 2023). "The levels of TNF-α, IL-1β, and IL-6 in whey from cows with mastitis were significantly higher than those from normal cows (p < 0.01)." (PMID 37175449, 2023). "The pro-inflammatory cytokines IL-12, IL-6, TNF-α, and IL-1β were found to be significantly elevated in lactating cows suffering from clinical mastitis." (PMID 36899749, 2023). "The serum TNF-α, IL-1β, and IL-6 levels of the cows with mastitis fed PUE root on day 7 were significantly lower than those on day 0 (p < 0.01), but there was no change in the healthy cows after the 7th day of the PUE addition." (PMID 37175449, 2023). "Supplementing with selenium was shown to significantly curtail the expression of NLRP3 inflammasome and proinflammatory cytokines IL-1β/IL-18, thereby mitigating the abnormal inflammatory response and consequently preventing mastitis in mice." (PMID 38259482, 2023). "TNF‐α and IL‐1β are important inflammatory cytokines that play critical role in the development of mastitis." (PMID 37328960, 2023). "As expected, a significant increase in the concentrations of proinflammatory cytokines, including TNF, IL6, and IL1β, in the serum and mammary glands of clinical mastitis cases has been observed in several previous studies." (PMID 37620551, 2023). "Increased levels of TNF-α and IL-1β in subclinical mastitis were discovered in this study, suggesting that they play a role in the early stages of mastitis development." (PMID 36899749, 2023). "Our results showed that Z-d14CFR enhanced bacterial clearance and reduced neutrophils infiltration and pro-inflammatory cytokines (TNF-α, IL-1β) expression, hence alleviated E. coli-induced inflammation in a murine model of mastitis." (PMID 35563007, 2022).
mastitis (continued). "It is observed that pathogenic activated NF-κB and MAPKs pathways caused overexpression of pro-inflammatory cytokines (IL-1β, IL-6, and TNF-α) in mastitis." (PMID 36145063, 2022). "The supplementation of selenium significantly downregulated the expression of NLRP3 inflammasome and proinflammatory cytokines IL-1β/IL-18, which activated the abnormal inflammatory response, resulting in mastitis in mice." (PMID 35453342, 2022). "In animal models of LPS-induced mastitis, melatonin has been shown to decrease the inflammatory response by reducing oxidative stress and pro-inflammatory cytokines such as IL-1β, IL-6, GM-CSF57,58." (PMID 34400791, 2022). "The RT-qPCR technique detected the mRNA expressions levels of TNF-α, IL-6, and IL-1β to evaluate the effects of L. plantarum KLDS 1.0344 on LPS-induced mastitis using isolated bMEC." (PMID 34858427, 2021). "The proteins crucial for acute mastitis (IL-18, Il-1β, TNFα, CCL2, CCR1) demonstrate low expression." (PMID 34663465, 2021). "LPS induces the expression of inflammatory cytokines such as TNF-α, IL-6, and IL-1β in the mammary glands, leading to mastitis in cows." (PMID 34858427, 2021). "Lactating cows with clinical mastitis and subclinical mastitis showed a marked increase in interleukin (IL)-2, IL-6, IL-1β, and tumor necrosis factor (TNF)-α." (PMID 34827839, 2021). "Analysis of cytokines showed that cows with mastitis significantly increased the levels of IL-1β and TNF-α." (PMID 34222051, 2021). "LPS can increase the expression of IL-6, TNF-α, and IL-1β in the mammary glands of dairy cows, which leads to the occurrence and development of mastitis." (PMID 32397071, 2020). "This pathway modulates the expression of many inflammation-related genes (such as inflammatory cytokines TNF-α, IL-1β, and IL-6), especially in mastitis." (PMID 32754201, 2020). "Real-time (RT)-PCR showed that, compared with those in the healthy dairy cows, the mRNA levels of IL-6, TNF-α, and IL-1β in the mastitis dairy cows increased significantly." (PMID 32397071, 2020). "Compared with those in the untreated mastitis group, the somatic cell counts (SCCs) and the expression of IL-6, IL-1β, and TNF-α in the blood and milk were lower." (PMID 32397071, 2020). "Supplementation of the mixture of LAB and yeast decreased the milk concentration of TNF-α, IL-1β and IL-6 compared with mastitis cows, while single use of yeast or LAB was unable to reduce the concentration of those inflammation cytokine concentration." (PMID 31997024, 2020). "The expression of IL-1β was significantly up-regulated in both clinical mastitis bPBLs and LPS-stimulated bMECs, suggesting that it is essential in bovine mastitis." (PMID 31447828, 2019). "LPS can stimulate mammary epithelial cells to produce the inflammatory cytokines TNF-α, IL-1β, and IL-6, which can interact with and regulate the occurrence and outcome of mastitis." (PMID 29849710, 2018). "We analyzed TNF-α, IL-1β, IL-6 and IL-10 levels in mouse mastitis model and the mammary epithelial cells by qRT-PCR and ELISA." (PMID 29340029, 2017). "In the present study, CD14, TNF-α, MD-2, IL-1β, NF-κB, and IL-12 gene expression was decreased in tissue affected by mastitis compared to normal mammary tissue, which is consistent with suppression of NF-κB activity and pro-inflammatory cytokine production." (PMID 25706977, 2015). "On the contrary, CD14, TNF-α, MD-2, IL-1β, NF-kB, and IL-12 expression levels were decreased in mastitis tissue with respect to normal tissue." (PMID 25706977, 2015). "Although the genes relevant to milk production are down-regulated in mastitis, lactoferrin and inflammatory cytokines such as interleukin (IL)-1β, IL-6, and tumor necrosis factor-α are up-regulated." (PMID 24308795, 2013).
mastitis (continued). "In vivo, intramammary infusion of TF via the teat canal into the infected quarter of cows with subclinical mastitis downregulated IL-1β/IL-6 mRNA, upregulated TJ genes, and reduced both MLCK expression and the phosphorylation of myosin light chain (MLC), p65, and TAK1." (PMID 41678235, 2026). "Additionally, the expression levels of pro‐inflammatory cytokines IL‐6, TNFα, and IL‐1β were markedly increased (P < 0.01), confirming the successful establishment of the mastitis model." (PMID 40552401, 2025). "A reduction in the IL-1β, IL-6 and IL-8 levels in cows fed Macleaya extract may indicate the resolution of inflammation or successful treatment for mastitis." (PMID 40303387, 2025). "Moreover, Mansour and Zeitoun have demonstrated that high levels of peripheral cytokines such as TNF-α, IL-6, IL-1β, and IFN-γ cause reproductive failure in buffalo cows suffering from either clinical or sub-clinical mastitis." (PMID 39858163, 2025). "Notably, TNF-α, IL-1β, and IL-6 gene expression in lipopolysaccharide (LPS)-challenged mastitis models peaked at three hours, followed by a gradual decline, reaching the lowest levels at 12 h in liver and udder tissue cells." (PMID 40564979, 2025). "Moreover, as one of the most typical messengers in the inflammation family, the expression levels of IL-1β, IL-6, and TNF-α can be used to better evaluate the damage caused by mastitis." (PMID 40438409, 2025). "Notably, CB treatment in MAC-T cells and mouse mastitis models markedly reduced the expression of IL-1β, TNF-α, and NLRP3, indicating potent anti-inflammatory effects similar to those observed with other natural compounds such as allicin and lentinan." (PMID 40243637, 2025). "Similarly, serum levels of TNF-α, IL-1β, and IL-6 were significantly higher in mastitis cows than in the control cows (p < 0.01)." (PMID 37175449, 2023). "TAC, Fb, ferritin, IL-1α, and IL-1β are good biomarkers for camel mastitis." (PMID 37534071, 2023). "Leaves extract reduced IL-1β levels in the tissues of Sprague-Dawley rats suffering from mastitis." (PMID 35744969, 2022). "The results showed that LGR-1 pretreatment had preventive and protective effects on E. coli induced mastitis, and could reduce cytokines levels such as IL-1β and TNF-α." (PMID 34594329, 2021). "A hypothetical schematic illustration of mitochondrial caspase-induced apoptotic pathway and NF-κB subunit 65 transiting into the nucleus in protothecal mastitis was consistent with reports in bMECs, wherein P. zopfii GT-II regulated transcription of pro-inflammatory genes like IL-1β and TNF-α35." (PMID 31959834, 2020). "The temporal sequences of SYK, PTK2B, TLR4, and IL-1β expression are similar, suggesting that there might be an immune response pathway in bMECs participating in bovine mastitis inflammatory response." (PMID 31447828, 2019). "DEGS such as IL10, CCL5, IL1B, OSM, TNFRSF1B, IL7, and CCR3, among others, implicated in these pathways, may play a crucial role in the development of subclinical mastitis in Bactrian camels, though further analysis is needed to explore their potential functions." (PMID 40005880, 2025). "However, when mice developed mastitis caused by Coagulase-negative staphylococci (CNS; Staphylococcus aureus, S. chromogenes, S. fleurettii), the inoculated S. aureus produced IL-6 and IL-1β but not TNF-α." (PMID 41148692, 2025). "Furthermore, IL1B is reported as a hub molecule in cattle mastitis." (PMID 34222390, 2021). "Based on significantly increased TLR4, IκB, TNF-α, IL-1β protein expressions, and NF-κB nuclear protein expression induced by E. coli, we inferred that it activated TLR4/NF-κB signaling pathways in bMECs and macrophages, consistent with E. coli causing mastitis through the TLR4/NF-κB pathway." (PMID 32733409, 2020). "Therefore, we hypothesized that SYK and TNFRSF21 may be involved in the NF-κB pathway, stimulating IL-1β secretion and promote mastitis inflammation in both bPBLs and bMECs." (PMID 31447828, 2019).
mastitis (continued). "Studies have shown that PS can effectively alleviate Staphylococcus aureus-induced mastitis by inhibiting the activation of pro-inflammatory signaling pathways such as NF-κB/NLRP3, reducing the release of inflammatory factors such as IL-1β and TNF-α." (PMID 41596521, 2026). "Utilizing the PPI network, the topological parameters of Betweenness unDir, Closeness unDir, and Degree unDir were employed to predict the core targets for mint in treating mastitis in dairy cows, which include TNF, IL–6, STAT–3, IL–1β, FGF–2, IFNG, and ESR–1." (PMID 40005889, 2025). "Mouse mastitis induced in this study by S. aureus was characterized by a broad increase in proinflammatory cytokines, particularly for IFN-γ, IL-1β, IL-6, and GM-CSF to stimulate and recruit macrophages and neutrophils as is expected for S. aureus IMIs." (PMID 40757863, 2025). "In conditions such as mastitis, the release of pro-inflammatory cytokines, including TNF-α, IL-1β, IL-6, and IL-8, significantly intensifies the inflammatory response, thereby exacerbating tissue damage and pathological alterations." (PMID 40666730, 2025). "During mastitis, mammary tissues exhibit elevated levels of inflammatory factors such as TNF-α, IL-6, IL-8, and IL-1β." (PMID 39860009, 2025). "The HC group exhibited disrupted ruminal microbiota, elevated serum levels of LPS, TNF-α, and IL-1β, and a markedly increased milk somatic cell count (SCC) exceeding 500,000/mL, indicating mastitis." (PMID 41362615, 2025). "According to Western blotting results, the mammary gland with subclinical bovine mastitis exhibited obviously increased protein expressions concerning ASC, cleaved-caspase-1, NLRP3, and IL-1β compared with the healthy ones." (PMID 39765775, 2024). "Gambogic acid (GA) was also reported to alleviate LPS-induced mastitis by reducing IL-6, TNF-α, and IL-1β levels." (PMID 39199398, 2024). "The levels of IL-1β, IL-6, TNF-α, COX-2, and iNOS in the serum of cows with clinical mastitis were significantly higher than those in the healthy cows (p < 0.001)." (PMID 36875515, 2023). "When PUE was added to the dairy diet of the healthy cows and cows with mastitis, the levels of TNF-α, IL-1β, and IL-6 in the whey of the cows on day 7 were significantly lower than those on day 0 (p < 0.01)." (PMID 37175449, 2023). "In terms of hub-hub genes, we identified several crucial immune and inflammatory response genes, including TLR2, TLR474, TNF, IL1β, IL1A, IL675, JAK276,77, and IL1068, which play important roles in the pathogen-host interactions during mastitis." (PMID 37620551, 2023). "Our previous study has demonstrated that decreased autophagy-related protein expression level and increased IL-1β and NLRP3 inflammasome-related protein expression level are involved in the pathogenesis of mastitis." (PMID 36362066, 2022). "The mRNA results showed that the contents of inflammatory mediators IL-1β, IL-6, and TNF-α in mastitis tissues were significantly higher than those in the control group (p < 0.01)." (PMID 36355118, 2022). "Propionate decreased the inflammatory factors (IL-1β, IL-6, and TNF-α) via inhibiting NF-κB and HDAC in in-vitro and in-vivo mastitis models." (PMID 36145063, 2022). "The data also showed that SYK gene expression and protein levels have a strong consistency in bovine mastitis, and NLRP3, TLR4 and IL-1β as well." (PMID 36672605, 2022). "In concrete, it has been shown that the production of TNF-α and IL-1β and the phosphorylation of p65 NF-kB are reduced by DMI treatment in a mouse model of mastitis." (PMID 36555614, 2022). "MECs can synthesize and secrete inflammatory chemokines and pro-inflammatory cytokines such as interleukin-1 beta (IL-1β), interleukin-6 (IL-6), interleukin-8 (IL-8), and tumor necrosis factor (TNF-α), which are crucial for the occurrence of mastitis." (PMID 35681915, 2022).
mastitis (continued). "For example, treatment with Morin in LPS-induced mastitis and LPS-induced acute lung injury significant decreased the expression of inflammatory cytokines, including TNF-α, IL-1β, and IL-6." (PMID 35705830, 2022). "LEO attenuated inflammatory responses, which was supported by decreasing TNF-α and IL-1β production in LPS-treated microglia, inhibiting COX-2 mRNA and protein expression in LPS-induced mouse mastitis." (PMID 35883829, 2022). "In mastitis, immune cell activity is mainly regulated by the pro-inflammatory cytokines TNF-α, IL-1β and IL-6, which are typically pro-inflammatory cytokines." (PMID 36090098, 2022). "Up to the knowledge, Klebsiella pneumoniae promotes the production of the inflammatory cytokine genes IL-6, IL-8, IL-1β, and TNF-α in mastitis already after 6 h." (PMID 35335696, 2022). "They found higher serum levels of IL-1β and IL-2, TNF-α, IL-6, and IFN-γ in subclinical mastitis compared to control cows." (PMID 34484387, 2021). "The mRNA and protein expression of TLR4, NF-κB, IL-1β, and TNF-α were up-regulated in mastitis induced by LPS and activated the TLR4/NF-κB signaling pathway." (PMID 34692813, 2021). "The mammary epithelial cells and the resident macrophages are the first line to interact with pathogens at the onset of mastitis, and then, cytophagocytosis is activated, and pro-inflammatory cytokines such as TNF-α, IL-1β, and IL-8 are released." (PMID 35224069, 2021). "The levels of IL-1β, IL-6, and TNF-α were significantly higher with treatment, indicating that the cell model of mastitis had been successfully established." (PMID 34575880, 2021). "We found that gut dysbiotic mice had obvious mastitis features, including increased acinus damage, histological score, MPO activity and pro-inflammatory tumor necrosis factor (TNF)-α and IL-1β expression compared with the control mice." (PMID 34297785, 2021). "Previous studies have proved that reducing the production of proinflammatory cytokines, such as IL-1β, IL-6, and TNF-α, can reduce the effect of mastitis." (PMID 33488936, 2020). "The general process of mastitis is characterized by upregulated synthesis of certain pro-inflammatory cytokines, such as TNF-α and IL-1β." (PMID 32117805, 2020). "The expression of GPR109A, IL-6, IL-1β, and TNF-α in the mammary glands of the dairy cows with mastitis was significantly higher than it was in the glands of the healthy dairy cows." (PMID 32397071, 2020). "In this study, TNF-α, IL-6 and IL-1β levels were significantly increased in the LPS-induced mastitis model, and peiminine inhibited the production of TNF-α, IL-6 and IL-1β in a dose-dependent manner." (PMID 30200569, 2018). "Indirubin inhibited the expression of IL-1β, IL-6, and TNF-α in LPS-induced mouse mastitis in a dose-dependent manner." (PMID 28255203, 2017). "IL-1β, IL-6, and TNF-α expression significantly increased after LPS stimulation both in MMEC and in the mouse mastitis model." (PMID 28255203, 2017). "S. aureus-induced mastitis is related to many types of inflammatory cytokines such as TNF-α, IL-1β and IL-6." (PMID 28415707, 2017). "We analyzed the anti-inflammatory effects of Se on S. aureus mastitis by determining protein and mRNA levels of TNF-α, IL-1β, IL-6 and IL-10 by ELISA and qRT-PCR, respectively." (PMID 29340029, 2017). "The mRNA expression of genes responsible for the inflammatory response (TLR4, LBP, IL-1β, IL-6, IL-8, NF-κB and TNF-α) was significantly increased, consistent with the results of exogenous LPS-induced mastitis by infusion." (PMID 26893357, 2016). "TLR2, NOD2, and inflammatory cytokines (TNF-α, IL-1β, IL-6, CXCL1, IL-10, TGF-β1, and IFN-γ) are involved in the response to mastitis induced by S. aureus." (PMID 25990971, 2015).